CXCL16 (C-X-C motif chemokine ligand 16)
Diseases named in the same sentence as CXCL16 in open-access papers (continued):
Sharing a sentence is not in itself a finding about the gene and the disease.
cancer (continued). "Cancer cells expressed multiple SASP-associated CC (e.g., CCL20) and CXC (e.g., CXCL1, CXCL8, CXCL16) chemokines, which have been shown to be induced by radiotherapy in preclinical models." (PMID 40811032, 2025). "In Head-and-neck and lung tumor models, cancer vaccine immunization can drive local CXCL16 upregulation, CXCR6 expression on TRM precursors, and robust TRM recruitment, while impaired TRM cell seeding was observed in CXCR6-deficient mice." (PMID 40862776, 2025). "Research indicates that cancer‐associated fibroblasts (CAFs) secrete elevated levels of CCL2, CCL5, CCL7, and CXCL16, which facilitate the migration and invasion of HCC cells." (PMID 40062588, 2025). "CXCL16 further remodels the TME by reprogramming TAMs, Cancer-Associated Fibroblasts (CAFs), and Myeloid-Derived Suppressor Cells (MDSCs), highlighting its therapeutic duality." (PMID 40552145, 2025). "In cancer, CXCL16 exerts paradoxical roles: via CXCR6 activation, it fuels tumor proliferation, invasion, and VEGF/MMP-driven angiogenesis, yet orchestrates antitumor immunity by recruiting NKT cells." (PMID 40552145, 2025). "In SCC, we observed increased expression of CXCR6, the receptor for Carcinoma 3's CXCL16, specifically in Tregs." (PMID 40776410, 2025). "In NSCLC, the CXCL16 expression of cancer and stromal cells was identified as a positive prognostic marker during immunohistochemistry." (PMID 38928238, 2024). "Therapeutic Targets: The involvement of CXCL2 and CXCL16 in cancer progression and metastasis highlights their potential as therapeutic targets." (PMID 39546375, 2024). "PDE5 activity supports stromal fibroblasts, which produce and secrete chemokines like CXCL16, promoting cancer progression." (PMID 39355618, 2024). "In thyroid cancer, CXCL16 was found to increase the infiltration of M2 macrophages and resulted in angiogenesis and a more aggressive cancer phenotype." (PMID 38928238, 2024). "Chemokines, such as CCL28, CXCL8, and CXCL16, and chemokine receptors, including CCR1, CCR8, and CXCR2, were positively linked to DLAT expression in various cancers." (PMID 37199628, 2023). "Currently, CXCL16 had to be verified to play an essential role in the carcinogenesis of various cancer and cancer therapy." (PMID 36676763, 2023). "Previous studies showed that higher CXCL16 expression was associated with M2‐macrophage infiltration and enhanced angiogenesis in thyroid cancer, and TAM promoted cancer metastasis by enhancing CXCL16–CXCR6 pathway in ovarian carcinoma." (PMID 36587392, 2023). "Because of the expression of both CXCR6 and CXCL16 by many cell types, this tandem has a lot of effects on cancer fate." (PMID 36429101, 2022). "HIF-dependent expression of CXCL16 and its endothelial cell receptor CXCR6 have previously been reported in response to hypoxia, and expression of CXCL16 has been reported to stimulate angiogenesis in cancer." (PMID 35235351, 2022). "The relative levels of CXC chemokines (A), CXCL5 (B) and CXCL16 (D) in multiple cancer types and the relative levels of CXC chemokines in PDAC (C)." (PMID 35468838, 2022). "CXCL16 is an important chemokine and can be secreted by NK cells, DCs as well as various types of cancer cells." (PMID 35959371, 2022). "On the other hand, soluble CXCL16 (sCXCL16) is implicated in instigating increased migratory and invasive potential of high CXCR6-expressing cancer cells." (PMID 34298782, 2021). "CXCL16 is also expressed in various cancers, including prostate, non-small cell lung, colorectal, and breast." (PMID 34298782, 2021). "When treating fibroblasts associated to breast cancer cells with sildenafil and vardenafil, CXCL16 levels are dropped, therefore cancer promotion is reduced." (PMID 33718200, 2021). "BrCa cells stimulated with CXCL16 showed changes in the phosphorylation status of molecules key to cancer signaling." (PMID 34298782, 2021). "In our study, we found that the cancer stem-like cell cluster LuE2 secreted the specific cytokine Cxcl16 and Cxcl1." (PMID 34675206, 2021).
cancer (continued). "At the same time, factors secreted from the monocytes are also important in the induction of CXCL16 expression and, therefore, this process requires the participation of three types of cell: cancer cells, monocytes, and fibroblasts." (PMID 33800554, 2021). "PDE5 activates stromal fibroblasts, which produce and secrete chemokines like CXCL16, promoting cancer progression." (PMID 33718200, 2021). "For this reason, it is postulated to use CXCL16-neutralizing antibody or CXCR6 inhibitors during cancer treatment with docetaxel or cisplatin in order to improve the applied therapies." (PMID 33800554, 2021). "Although various chemokines have pro-tumorigenic actions in cancers, the effects of CXCL16 remain controversial." (PMID 31527616, 2019). "CXCL16, deemed as a unique chemokine, exists both in transmembrane or soluble forms, and the CXCL16/CXCR6 chemokine axis is recently occupying roles in cancer as regulators of cell proliferation, invasion and metastases." (PMID 30996686, 2019). "In this study we have established the association of CXCR6 with aggressive phenotype of OVCa and have shown significance of CXCR6 and CXCL16 in the biological processes a cancer cell utilizes to establish metastatic lesions." (PMID 30792527, 2019). "The PI3K/PTEN/AKT/mechanistic target of rapamycin (mTOR) signal pathway has been clarified to be involved in the CXCR6/CXCL16 biological axis in the cancer realm." (PMID 30620718, 2019). "CXCL16, as a member of the chemokine family, is expressed and released by numerous types of cells such as dendritic, liver sinusoidal endothelial and cancer cells and macrophages." (PMID 30620718, 2019). "Plasma CXCL16 levels were elevated for 4 weeks after minimally invasive colorectal resection for cancer." (PMID 29981574, 2018). "The unique expression of CXCL16 by brain metastasis CAFs provides an important area of cancer research that will further our understanding of metastatic progression." (PMID 28649646, 2017). "Transmembrane and soluble CXCL16 play divergent roles in homeostasis, inflammation, and cancer, which can be beneficial or detrimental." (PMID 28267793, 2017). "Accordingly, urine supernatant from high grade UC patients had high urinary CXCL16 concentrations; whereas, CXCL16 staining of cancer cells was low in the corresponding tissue." (PMID 29285224, 2017). "CXCL16 is a ligand of the chemokine receptor CXCR6 involved in regulating cancer invasion and metastasis." (PMID 29242629, 2017). "We have shown that high stromal cell CXCL16 expression and combined high stromal and cancer cell CXCL16 are independent positive prognostic factors in NSCLC." (PMID 26021984, 2015). "In a previous study, CXCL16 was found not only in immune cells, but also expressed constitutively in cancer cells of different origins." (PMID 25909173, 2015). "Significant clinicopathologic variables were entered into multivariate analysis in two separate models, one with stromal CXCL16 expression variable (model 1) and one with the co-expression variable of cancer and stromal cell CXCL16 (model 2)." (PMID 26021984, 2015). "The combined high expression of CXCL16 in stromal and cancer cells was an independent positive prognostic factor for DSS in model 2 (HR: 0.42; 95 % CI: 0.20 – 0.88, P = 0.022) when compared to the combined low expression." (PMID 26021984, 2015). "The increased survival seen in patients with combined high CXCL16 expression in cancer and stromal cells led us to investigate the effect of CXCL16 on cell proliferation." (PMID 26021984, 2015). "Because cancer cell migration and metastasis share patterns with leukocyte trafficking, attention has been focused on the role of CXCL16 in cancer progression." (PMID 24864132, 2014). "These limited reports imply different functions for CXCL16 depending on the location of its expression in cancer patients." (PMID 24864132, 2014). "To characterize it, we employed flow cytometry to quantify CXCL16 localized on cell surfaces in living cancer cells." (PMID 24864132, 2014).
cancer (continued). "This cell line was cultured in a polyclonal population with a different expression level of CXCL16 in the antibiotic G418 to maintain the heterozygous characteristics of cancer cells." (PMID 25495942, 2014). "Immunohistochemical staining data from patients with colorectal or renal cancer correlated better long-term prognosis with stronger CXCL16 staining in cancer tissues." (PMID 24864132, 2014). "These observed differences between TM-CXCL16 and sCXCL16 indicate a complicated function for CXCL16 in cancer." (PMID 24864132, 2014). "Soluble CXCL16 chemokine induces proliferation and migration of cancer cells, further regulates invasion and metastasis of cancer." (PMID 23941552, 2013). "Recently, it was established that both the chemokine receptor CXCR6 and its ligand CXCL16 are not only expressed by immune cells, but also by carcinomas." (PMID 20664601, 2010). "In a recent paper, binding of CXCR6 by the cleaved soluble fragment of its membrane-bound ligand CXCL16 (“sCXCL16”) was shown to enhance the proliferation of carcinoma cell lines." (PMID 21203549, 2010). "Consistent with these in vitro data, cancer cells expressing Ki67, a cellular marker for proliferation, also expressed both CXCL16 and CXCR6." (PMID 19690611, 2009). "Moreover, PFKP-overexpressing cancer cells stimulate cancer-associated fibroblasts (CAFs), which in turn augment CD133+ CSLC formation via the CXCL16/CXCR6 axis, establishing a feedforward loop that reinforces chemoresistance." (PMID 42024199, 2026). "Furthermore, infection led to an increase in the expression of cancer progression-related chemokines Ccl5 and Cxcl16, being upregulated most prominently by SFV/TNFα and SFV/IFNγ." (PMID 40547518, 2025). "Furthermore, CXCR6 emerges as a pivotal marker for tissue-resident memory (TRM) cells across various cancer types and serves as the receptor for the chemokine CXCL16." (PMID 39835121, 2024). "For the discrimination of UCa cases from other cancer patients and controls (independent from UCa history), the sensitivities and specificities of CXCL16 based on the 95th percentile of CXCL16 in hospital controls from our previous study (648.5 pg/mg creatinine) were calculated." (PMID 39587670, 2024). "The potential increase of Cluster 0 cells after CXCL16 NAb might counteract the overall anti-cancer response." (PMID 37055410, 2023). "In summary, CXCL16 tend to have predominantly a pro-tumoral role through promoting an anti-inflammatory phenotype of TAMs, and by activating proliferative and invasive potentials of cancer cells." (PMID 36686729, 2022). "Next, we focus on the importance of CXCL16 in a variety of diseases, with an emphasis on cancer." (PMID 33800554, 2021). "CXCL16 may also be a marker of a patient’s response to cancer therapy, for example in the administration of bevacizumab to non-squamous non-small cell lung cancer patients." (PMID 33800554, 2021). "Nevertheless, the most important cells in the anti-cancer activity of CXCL16 are NKT cells." (PMID 33800554, 2021). "At the end of the article, we summarize the importance of CXCL16 in cancer therapy." (PMID 33800554, 2021). "For this reason, chronic hypoxia may increase the expression of CXCL16 in these cancer cells, although this still needs to be confirmed through further studies." (PMID 33800554, 2021). "Therefore, the aim of this review is to collect and summarize all available knowledge about CXCL16 to make it more accessible to scientists studying the role of chemokines in cancer." (PMID 33800554, 2021). "The results could contribute to the design of new highly specific CXCR6 antagonists for the pathologies in which the CXCR6‒CXCL16 axis is involved, like the metastasis of cancer cells and autoimmune pathologies." (PMID 33920834, 2021). "CXCL16 plays an important role in side effects or resistance to anti-cancer drugs." (PMID 33800554, 2021).
cancer (continued). "We found that 30 of these genes which included Nckap1l, Ncf1, Pla2g15, Unc93b1, Lrrc33, Rgs10, Gmfg, Rbm25, C3ar1, Ccdc88b, Fam105a, Gng11, Phc1, Rasa4, Dag1, Tyrobp, Tmsb4x, Cfp, Prkd1, Gp49a, Trem2, C1qc, Lyz2, Igfbp7, Rab30, Cxcl16, Egfl7, Ube2r2, Pltp, and Cfb, showed a relation with cancer." (PMID 32812032, 2020). "Still, the literature regarding the role of CXCL16 in human cancers is conflicting." (PMID 31527616, 2019). "CXCR6/CXCL16 axis is primarily expressed by immune cells and plays significant role in immune cell trafficking impacting innate and adaptive immune response against infection and cancer." (PMID 30792527, 2019). "Expression of CXCL16 is reported in many cancers including CRC." (PMID 29981574, 2018). "CXCR6 is expressed on various cancer types concomitant with high levels of CXCL16 in tumors." (PMID 28267793, 2017). "Blocking CXCR4 and/or CXCL16 neutralization, alone or in combination, resulted in significant inhibition of patient-derived cancer cells migration to brain metastatic CAF aggregates, further supporting the importance of CXCL16 and CXCL12 in migration of CTCs into brain-associated microenvironment." (PMID 28649646, 2017). "In addition to the expression of CXCL16 on DCs, macrophages, and B cells, CXCL16 is expressed by a variety of mouse and human cancer cells." (PMID 27471636, 2016). "Notably, CCL20 and CXCL16 mRNA were found to be more strongly expressed in cancer tissue than in unaffected tissue." (PMID 27517754, 2016). "Therefore, CXCR6/CXCL16 co-stimulatory interactions represent a potential target for manipulation in cancer therapies, where a boost in the Th1 IFNγ response is desired." (PMID 27471636, 2016). "Concomitantly, soluble CXCL16 contributed by LuCa cells could saturate CXCR6 on lymphocytes and block their ability to detect cancer by mimicking trans-membrane CXCL16." (PMID 25888629, 2015). "Furthermore, irradiated tissue releases various chemoattractant factors, such as CCL11 or CXCL16, and promotes infiltration of lymphocytes into the cancer tissue." (PMID 25890185, 2015). "Although further studies are required to obtain greater insight into the function of this molecule, CXCL16 may have a vital role in the study of cancer immunology and cancer biology." (PMID 25495942, 2014). "In cancer, CXCL16 may be directly targetable as monotherapy and as a therapeutic adjuvant." (PMID 40862776, 2025). "Additionally, interactions between FOXP3high/+ Tregs and cancer cells may be involved in Treg mobilization (CXCR6/CXCL16) and activity (TIGIT/PVR)." (PMID 40164596, 2025). "These parameters include, first of all, the CXCL14/CEA and CXCL16/CEA indexes, which showed extremely high diagnostic usefulness and the possibility of assessing and differentiating between CRC and healthy volunteers, as well as between the stages of cancer advancement." (PMID 37240636, 2023). "In some types of cancer cells, increased expression of CXCL16 may reduce proliferation." (PMID 33800554, 2021). "In the study of the relationship between tamoxifen resistance and cancer‐associated fibroblasts, it was found that after TAM treatment, the secretion of CXCL16 increased under the guidance of G‐protein coupled receptor 30, and the exocrine CXCL16 promoted the migration and invasion of MCF‐7 cells." (PMID 32253815, 2020). "Therefore, CXCL16 may be an interesting candidate marker for follow-up studies to assess its predictive value for cancer recurrence and progression." (PMID 29285224, 2017). "This might indicate the presence of accelerated damage due to the production of inflammatory mediators (e.g. CXCL-16, IL-17, and BMP-2), since high levels of these circulating factors clearly represent a risk for cardiovascular disease, cancer, and metabolic disturbances." (PMID 28293269, 2017).
cancer (continued). "CXCL16 may be an attractive candidate for gene therapy in colorectal liver metastasis because of its effective dual approach of not only accumulating TAMs, but also increasing cancer cell apoptosis." (PMID 25495942, 2014). "In particular, recent studies have verified the over-expression of CXCL16 and/or CXCR6 in several types of human cancers and CXCL16 could stimulate the growth, migration, invasion and activation of AKT signaling pathway of cancer cells via its’ receptor CXCR6 in vitro." (PMID 24897301, 2014). "Moreover, CXCL16 enhanced the growth of CXCR6-expressing cancer and primary CD4 T cells." (PMID 19690611, 2009). "Expression levels of CXCL16 and CXCR6 on cancer cells correlated with poor prognostic features including high-stage and high-grade, and expression also correlated with post-inflammatory changes in the cancer stroma as revealed by loss of alpha-smooth muscle actin." (PMID 19690611, 2009). "Proteomic analysis of mouse plasma revealed increased secretion of cancer-related proteins (CXCL13, CXCL16, and MMP2) in the MCPIP1-mutant group." (PMID 39815326, 2025). "The heatmap displayed that GPX4 expression was highly correlated with the levels of numerous chemokines and chemokine receptors, such as CXCL16, CCL28, CX3CL1, CCL5, CCR10, CXCR5, and CXCR3, across the majority of cancer types." (PMID 41142608, 2025). "Analysis of mouse plasma revealed increased secretion of cancer-related proteins, such as CXCL13, CXCL16, MMP2, selectins, and pentraxin 2, in the group with MCPIP1 mutations." (PMID 39815326, 2025). "We next identified cells expressing the receptors CXCR6 and TNFRSF9, which correspond to their ligands CXCL16 and TNFSF9 in Carcinoma 3, particularly in SCC." (PMID 40776410, 2025). "In summary, we confirmed our previously identified methylation biomarkers ALOX5, TRPS1 and Chromosome 16 as well as our protein biomarkers CXCL16 and TGFBI to discriminate UCa from cancer-free controls in a large and independent collective." (PMID 39587670, 2024). "Generally, CAFs promote the malignant progression of cancer cells by secreting cytokines, chemokines, and proangiogenic factors, including CXCL12, TGF-β1, VEGF, PDCF, IL-6 and CXCL16." (PMID 38057830, 2023). "For chemokines, our results suggest that the KIFscore was negatively correlated with CXCL16 and CCL14 in the vast majority of cancers." (PMID 37711200, 2023). "CXCL16 is expressed by a wide number of cells within the TME, such as endothelial, mesenchymal stem cells, macrophages, MDSCs, CAFs and cancer cells too." (PMID 36429101, 2022). "CXCL16 inhibits liver metastasis via the recruitment of CXCR6-expressing T cells and invariant NKT (iNKT) cells and improves the survival of cancer patients." (PMID 35320940, 2022). "It was also reported that CD8+T cells which express CXCR6 are recruited by CXCL16 secreted by cancer cells, hence, enhanced CXCR6 expression in CD8+T cells enhances cancer T cell infiltration and limits EOC progression." (PMID 35269786, 2022). "Expression analysis of CXCL16 and ADAM10 in BrCa tissues is important because of the CXCL16-CXCR6 ligand-receptor system in cancer development and the ability of ADAM10 to cleave Tm-CXCL16." (PMID 34298782, 2021). "The expression of CXCL16 was dominant in the stromal cells, whereas VEGF‐A tended to be expressed more in the cancer cells (Figure SS1)." (PMID 32163231, 2020). "The expression levels of CXCL16 and VEGF‐A in cancer cells or stromal cells were statistically compared using chi‐square tests." (PMID 32163231, 2020). "Evidence shows that red bone marrow attracts migrating cancer cells via chemotaxis with stromal derived factor-1 (SDF-1) and CXCL16." (PMID 31456685, 2019). "There are reports shown that fibroblasts involve in the cross-talk of cancer cells and fibroblasts by secreting CCL2, CCL5, CXCL1, CXCL6, CXCL12, IL6, CXCL16 and others." (PMID 28465475, 2017).